PRAME (PRAME nuclear receptor transcriptional regulator)
Diseases named in the same sentence as PRAME in open-access papers (continued):
Sharing a sentence is not in itself a finding about the gene and the disease.
cancer (continued). "The overall results suggest that PRAME overexpression is an indicator of poor OS in patients with cancer." (PMID 33381588, 2020). "Our group has described TCRms specific for a cancer germline antigen, PRAME, which is widely expressed in various cancers (recognizing ALYVDSLFFL/HLA-A*02:01), and FOXP3, the hallmark protein for Tregs (recognizing TLIRWAILEA/HLA-A*02:01)." (PMID 33569049, 2020). "The overall results suggest that PRAME overexpression is an indicator of poor MFS in patients with cancer." (PMID 33381588, 2020). "PRAME is highly expressed in different types of cancers and is involved in cell proliferation, apoptosis, differentiation and metastasis as well as the outcomes of patients with cancer." (PMID 32022332, 2020). "Further, PRAME has been shown to increase cell proliferation and inhibit apoptosis in various cancer models." (PMID 30602372, 2019). "The restricted re-expression of PRAME across malignancies renders it a candidate target for cancer treatment and has sparked numerous studies on the development and evaluation of immune-based interventions targeting PRAME." (PMID 31311081, 2019). "PRAME is among of the most widely studied cancer/testis antigens and has been proposed as a promising cancer biomarker and therapeutic target." (PMID 29029482, 2017). "Therapeutic cancer vaccines consisting of PRAME peptides have entered clinical trials for patients with different types of solid tumors and have not shown any major toxicities." (PMID 29029482, 2017). "In order to study and evaluate PRAME as a cancer specific target with translational capability, we synthesized a radiolabeled MPA1." (PMID 29029482, 2017). "These monoclonals would then be ideally suited for examining therapeutic potential and off-target binding, with the overarching long-term goal to develop a therapeutic selective for PRAME positive cancers." (PMID 29029482, 2017). "Earlier studies in cancer cells demonstrated that PRAME functions either as a transcription suppressor of RA signaling, or as a transcription activator on promoter regions bound by NFY." (PMID 23565261, 2013). "PRAME belongs to a group of cancer/testis antigens (CTAs) that are characterized by their restricted expression in normal gametogenic tissues and a variety of tumors." (PMID 23565261, 2013). "Expression and function of PRAME has been extensively studied in a variety of cancer cells, and high PRAME expression correlates with cancer progression." (PMID 23565261, 2013). "Endogenous and overexpressed PRAME proteins were observed in both the nucleus and cytoplasmic compartments in different cancer cell lines." (PMID 23460923, 2013). "Consistent with the literature, we found that PRAME is expressed only in very few normal adult tissues while it is upregulated in several cancers." (PMID 22912744, 2012). "Hypo-methylation of PRAME has been demonstrated to be responsible for the increased expression in various types of cancer." (PMID 23144859, 2012). "The PRAME gene family belongs to the group of cancer/testis genes whose expression is restricted primarily to the testis and a variety of cancers." (PMID 21347312, 2011). "Like other cancer-testis antigens, the PRAME gene is hypermethylated in normal tissues such as bone marrow, but hypomethylated in malignant cells." (PMID 20799951, 2010). "Although the role of PRAME in acute leukaemia and other cancers is complex, it has promise both as a cancer biomarker and as a therapeutic target." (PMID 20799951, 2010). "Preferentially expressed Antigen in Melanoma (PRAME), a multifunctional cancer testicular antigen expressed in normal and neoplastic tissue, has proven to be a useful diagnostic tool in the differential diagnosis between benign and malignant melanocytic lesions." (PMID 41369373, 2025). "These ligands, such as programmed cell death ligand 1, CD86, GAL-9, and VISTA, may partly explain the reduced T-cell-mediated activation and killing of PRAME-overexpressing cancer cells." (PMID 40933628, 2025).
cancer (continued). "Hence, to study the therapeutic implications of PRAME expression in KC, it was imperative to study retinoid response in cancer models." (PMID 40101298, 2025). "Our analysis identified LMO1 and PRAME as promising prognostic biomarkers in BC patients, thereby validating our framework as a robust, generalizable approach for discovering prognostic biomarkers in cancer." (PMID 40076569, 2025). "However, in other cancers, the prognostic significance of PRAME expression is less clear, and further research is needed to understand its role fully." (PMID 38338862, 2024). "Numerous functions have been attributed to PRAME, but it remains unclear how PRAME drives cancer progression." (PMID 38030788, 2024). "Given that increased PRAME expression is associated with poorer prognosis in other cancers, these data are not surprising." (PMID 39451258, 2024). "However, PRAME activation directly correlates with adverse clinical outcomes in several cancer types and is thought to contribute to tumorigenesis through inhibition of the retinoic-acid pathways for growth arrest and apoptosis." (PMID 39091741, 2024). "Each of these cancers can exhibit varying levels of PRAME expression, which may correlate with clinical outcomes." (PMID 38338862, 2024). "Although histone acetylation, as a determinant of PRAME expression, warrants further studies, there may be a rationale for the use of anti-PRAME immunotherapy in combination with histone deacetylase inhibitors in cancer treatment." (PMID 38541782, 2024). "PRAME stands out as one of the most widely expressed cancer-testis antigens." (PMID 39204391, 2024). "PRAME constitutes one of the largest multi-copy gene families in Eutherians, encoding cancer-testis antigens (CTAs) with leucine-rich repeats (LRR) domains, highly expressed in cancer cells and gametogenic germ cells." (PMID 38395975, 2024). "PRAME is known to regulate essential cellular processes, such as inhibition of differentiation and apoptosis, promotion of proliferation, and evading immune responses in cancer cells." (PMID 38395975, 2024). "Interestingly, several studies exploring CTA and PRAME biology in cancer note similar hypomethylation patterns for CTA genes." (PMID 39451258, 2024). "Two other genes, ZNF385C and PRAME, were previously reported to be overexpressed in specific cancer types but with largely unknown molecular functions." (PMID 36982699, 2023). "In BCa, PRAME could increase cancer cell motility through reprogramming genes of epithelial-to-mesenchymal transition, thus promoting BCa progression." (PMID 37728703, 2023). "Thus, modulation of PRAME expression is considered a viable strategy to improve the efficacy of immune checkpoint inhibitors in cancers." (PMID 36980267, 2023). "The expression of PRAME has been reported in various types of malignant tumor." (PMID 38132219, 2023). "Interestingly, this cytogenetic band included genes of the PRAME regulon that is known to confer a growth advantage to cancer cells." (PMID 36230884, 2022). "PRAME is highlighted as a new cancer therapeutic target of T cell– or antibody-based immunotherapies, with promising antitumor responses in early-phase clinical trials and preclinical models for several types of cancers." (PMID 35380993, 2022). "Additionally, PRAME is overexpressed in a variety of cancers, but its molecular functions are poorly understood." (PMID 36292630, 2022). "Radioimmunoconjugates and Ab-drug conjugates may also be explored in the context of targeting PRAME-positive cancer cells in an effort to provide effectiveness against cancer cells." (PMID 33804612, 2021). "Moreover, PRAME overexpressing cells dampened (p ≤ 0.05) cytolytic potential, as observed by a decrease in cancer cell death following direct co‐culture." (PMID 34612587, 2021). "Data from the cancer biology research suggest that PRAME’s role in transcriptional regulation could be multifaceted." (PMID 34074333, 2021).
cancer (continued). "Interestingly, we found that PRAME expression in cancer cells modulates T cell activation through direct cell‐cell interaction as well as through indirect contact by the secretion of soluble mediators." (PMID 34612587, 2021). "This discrepancy suggests that the role of PRAME in cancer may differ depending on tissue‐ and context‐specific features and warrants further investigation." (PMID 34612587, 2021). "Although these two phase I studies revealed PRAME as a potential target in cancer vaccines, more data concerning overall survival and disease-free survival and further clinical trials would make PRAME a more convincing targeted molecule for cancer vaccine design." (PMID 33503926, 2021). "Among all CGA candidates, melanoma-associated antigen A3 (MAGE-A3), New York esophageal squamous cell carcinoma-1 (NY-ESO-1) antigen, and preferentially expressed antigen in melanoma (PRAME) have been well-studied and proved to be promising cancer vaccine targets." (PMID 33503926, 2021). "Preferentially Expressed Antigen in Melanoma (PRAME) is a cancer/testis antigen (CTA)." (PMID 35076507, 2021). "PRAME, a testis-selective cancer testis antigen (CTA), is associated with cell proliferation, apoptosis, differentiation, and the outcomes and risk of metastasis in human cancers." (PMID 33997099, 2021). "To demonstrate the viability of the approach, we used an antibody to PRAME (preferentially expressed antigen in melanoma), a cancer-testis protein that is overexpressed in a number of cancers and is thought to be suitable as a diagnostic and prognostic marker in anticancer therapy." (PMID 34884647, 2021). "Collectively, our findings support a potential dual purpose for targeting of PRAME in cancer; either through direct targeting of cancer cells based on PRAME immunogenicity or by inhibiting oncogenic traits of PRAME, or through indirect disruption of PRAME‐associated immunomodulation." (PMID 34612587, 2021). "PRAME knockdown was shown to decrease the proliferation of cancer cells." (PMID 33381588, 2020). "In summary, these data are suggesting that PRAME is tumorigenic and may serve as a prognostic biomarker for cancer." (PMID 33381588, 2020). "Genes related to B and T cell maturation (e.g. CD37, CD79B, JCHAIN, IGLL1, VPREB3, CD52), ribosomal protein genes (RPS-*, RPL-*) and cancer/stress genes (e.g. PRAME, ARHGDIB, FOS, JUN) were within the most significantly deregulated genes between clusters in those samples." (PMID 32415257, 2020). "Importantly, two gene families of these amplified regions, PRAME and CT45, had been reported to overexpressed in various cancer types and associated with cancer metastasis, indicating their potential as biomarkers for PM in GC patients." (PMID 31570735, 2019). "Given the widespread expression of PRAME across different cancers, it is important to consider its heterogeneity of expression, as this may limit the PRAME-specific therapeutic response." (PMID 31311081, 2019). "PRAME has emerged as a potential candidate target for immunotherapy, and we are currently awaiting the results from numerous clinical trials evaluating PRAME-specific cancer vaccines and adoptive T cell therapies." (PMID 31311081, 2019). "Moreover, increased PRAME expression was correlated with a worse survival, further supporting its clinical value as a prognostic biomarker and/or therapeutic target in cancer." (PMID 30602372, 2019). "Relative expression of PRAME or BOB1 in these cancer cell lines was analyzed by qPCR." (PMID 29707134, 2018). "Although PRAME has been extensively studied in tumorigenesis and cancer biology, and is being used as a biomarker for cancer diagnosis and antigen-specific cancer immunotherapy, the function of the PRAME gene family in gametogenesis and reproduction has not been characterized." (PMID 23565261, 2013).
cancer (continued). "However, overexpression of PRAME is frequently found in a wide variety of human cancers, including acute and chronic haematological tumours, synovial sarcoma, lung, breast, and renal carcinoma." (PMID 22912744, 2012). "Also, PRAME contributes to cancer progression by promoting EMT." (PMID 40868240, 2025). "Furthermore, a recent study showed that PRAME was significantly up-regulated in a large number of tumors, and its high expression was correlated with poor overall survival across many cancer types, based on a pan-cancer survival analysis." (PMID 40004764, 2025). "However, histone acetylation might be a common mechanism regulating the transcription of PRAME in distinct types of cancer." (PMID 38541782, 2024). "However, detailed molecular mechanisms regarding controlling PRAME expression and its downstream pathways remains unclear; moreover, these mechanisms might be different depending the origin of malignant tumors." (PMID 38132219, 2023). "Importantly, our data suggest that PRAME may be a broad, multi-cancer immunotherapy target in pediatric extracranial solid malignancies, similar to efforts in hematologic malignancies where clinical trials are underway (e.g., NCT02494167 and NCT02203903)." (PMID 34818552, 2021). "Furthermore, we discuss whether PRAME might be a promising target for potential immunotherapy in human malignant tumours." (PMID 32022332, 2020). "Moreover, we highlight whether PRAME might serve as a useful prognostic biomarker in numerous human cancers." (PMID 32022332, 2020). "However, the clinicopathological features and prognostic value of the PRAME expression in patients with cancer remain unclear." (PMID 33381588, 2020). "In addition, PRAME might serve as an attractive therapeutic target in the treatment of malignant tumors." (PMID 33381588, 2020). "Despite the lack of modulation of PRAME by MSX2, it will be of enormous interest to further explore how PRAME controls human mesenchymal development and whether PRAME promotes carcinogenesis by giving the cells mesenchymal characteristics during cancer progression." (PMID 30033084, 2018). "In cancers other than acute leukaemias, PRAME expression is associated with negative outcomes." (PMID 20799951, 2010). "Therefore, PRAME could be an ideal target for cancer immunotherapy." (PMID 39122001, 2024). "Preferentially expressed antigen in melanoma (PRAME), a member of the CTA gene family, was first reported as a cancer/testis antigen." (PMID 36980687, 2023). "Of 90 CTAs validated by RNA sequencing, eight CTAs (DPEP3, EZHIP, MAGEA4, MAGEB2, MAGEC2, PAGE1, PRAME, and TKTL1) were selected for immunohistochemical profiling in cancer tissues from 328 NSCLC patients." (PMID 37341056, 2023). "Therefore, PRAME expression might depend on the origin of the malignant tumors." (PMID 38132219, 2023). "This PRAME–RAR interaction inhibits transcriptional programmes involved in RA-induced differentiation, growth arrest and apoptosis, which results in the cancer phenotype." (PMID 36980267, 2023). "In particular, they include the MAGEA, B group, multiple SPANX members, and PRAME, which binds CT-GG cluster to the giant meiotic cluster of the human WGD+ cancer network." (PMID 36499258, 2022). "The binding specificity of the anti-PRAME 2D5 mAb was assessed by its ability to detect the endogenous PRAME by Western blotting and FACS analysis in cancer cell lines expressing the protein." (PMID 33804612, 2021). "Cancer testis antigens such as NY‐ESO‐1 and PRAME have been widely studied as candidate target for immunotherapy given their restricted expression patterns and immunogenic nature." (PMID 34612587, 2021). "As previously demonstrated, AURKB was correlated with FAM64A, PRAME, CDCA3, etc., which are all highly related to cancers." (PMID 33612479, 2021). "The differentially expressed CG genes (DE-CG genes) included cancer vaccine targets and genes with oncogenic function, including MAGEA, NY-ESO-1, XAGE-1, CT45, and PRAME." (PMID 32213861, 2020).
cancer (continued). "Targeting PRAME presents an attractive approach for CTA-based immunotherapy, as it displays few unique features in comparison to other cancer testis antigens, which are highlighted in this review." (PMID 31311081, 2019). "Interestingly, a number of genes encoding CTAs that are potentially useful for developing cancer vaccines were in the list of 63 CTA genes with higher expression levels in the higher-TMB subtype, such as MAGEA (MAGEA-1, 2, 3, 4, 6, 8, 9B, 10, 11, 12), NY-ESO-1, and PRAME." (PMID 30634925, 2019). "Upon mapping the list of peptides to genes and referencing those genes for tissue expression levels, we observed several known cancer targets with favorable therapeutic windows, including PHOX2B, PRAME, and SOX11, a primarily developmental transcription factor expressed in many different tumors." (PMID 41477871, 2026). "It is thought that PRAME plays a role in the malignant phenotype of some cancer cells including melanoma and other cutaneous and noncutaneous malignancies." (PMID 40933628, 2025). "Although PRAME is not uniformly expressed across all cancers, it is frequently overexpressed in a wide array of malignancies." (PMID 40868240, 2025). "Despite PRAME expression in cancer presumably being regulated by gene methylation, we found no relevant, direct correlation with DNA methylase/demethylase expression." (PMID 38541782, 2024). "In contrast, cancer cells that did not present PRAME-pHLA complexes on their cell surfaces (HLA-A*02:01– NSCLC cells: NCI-H1693 and PRAME– ovarian TYK-nu used as controls for these experiments) did not elicit T cell redirection and activation or cytotoxicity." (PMID 39659431, 2024). "The expression of PRAME is not universal among all cancers, but shows a broad pattern of upregulation in many of them." (PMID 38338862, 2024). "PRAME is a prominent member of the cancer testis antigen family of proteins that is expressed in various types of cancers but generally not in normal tissues apart from male germinal cells." (PMID 35380993, 2022). "We did identify a CTLA4+/TIM3+ CD8+ T cell subset, however, no significant changes in its frequency were observed in the presence of PRAME overexpressing cancer cells (data not shown)." (PMID 34612587, 2021). "Preferentially expressed antigen in melanoma (PRAME), which belongs to the cancer/testis antigen (CTA) gene family, plays a pivotal role in multiple cellular processes and immunotherapy response in human cancers." (PMID 32022332, 2020). "There was an obvious relationship between the high expression of PRAME and shorter OS in Asian patients with cancer (HR = 1.41, 95% CI: 1.02–1.95, P < 0.001) and non-Asian patients with cancers (HR = 2.36, 95% CI: 1.81–3.08, P < 0.001)." (PMID 33381588, 2020). "Cancer testis antigens are gaining interest as targets for adoptive T cell therapy with numerous preclinical studies and clinical trials focusing on NY-ESO-1, MAGE-A3 and PRAME." (PMID 31932876, 2020). "Furthermore, a microarray analysis of PRAME shRNA-silenced leukemic cells revealed that PRAME alters the expression of two additional genes, IL-8 and IGFBP2, that are potentially involved in carcinogenesis and cancer progression." (PMID 28903396, 2017). "Similarly to GAL3ST1, PRAME and FOXA3 genes were also silent under CTCF occupancy, but were activated upon CTCF and BORIS co-binding in both cancer and germ cells." (PMID 26268681, 2015). "Healthy neuronal tissues were negative overall for PRAME expression with the exception of healthy testis, hence its designation as a cancer/testis antigen." (PMID 26452036, 2015).